BRCA2 (BRCA2 DNA repair associated)
Diseases named in the same sentence as BRCA2 in open-access papers (continued):
Sharing a sentence is not in itself a finding about the gene and the disease.
cancer (continued). "One of the genes, originally named FANCD1, turned out to be BRCA2 (OMIM #600185) in which mono‐allelic mutations cause susceptibility to breast and other cancers, while biallelic mutations lead to FA." (PMID 30450770, 2018). "Surveys were sent to individuals for whom their insurer ordered genetic testing for the cancer susceptibility genes BCRA1 and BRCA2 over a 1 year time period that spanned the introduction of a GC-mandate policy." (PMID 29514700, 2018). "Remarkably, the patients diagnosed with both cancers showed a 50% rate of mutation detection, again with similar distribution in both genes: 69% detected in BRCA1, 27.6% in BRCA2, and 3.4% in both genes." (PMID 30103829, 2018). "Interaction of EMSY with exon 3 of wild-type BRCA2 (deleted in cancer) functionally inactivates BRCA2, suggesting a regulatory role for EMSY in the HRR pathway." (PMID 29459887, 2018). "Overall, this concept highlights Rad52 as a potential therapeutic target in tumors with inactive BRCA2 and helps explain why Rad52 gene amplifications are selected for in human cancers." (PMID 29548335, 2018). "Mendelian inheritance patterns are largely due to DNA alterations that give rise to pathogenic germline variants, or mutations in highly penetrant cancer predisposition genes such as in HOXB13 and BRCA2." (PMID 29690565, 2018). "Mutations in HR genes (e.g. BRCA1 and BRCA2) and their epigenetic status (e.g. BRCA1 silencing) have been linked to an increased risk of developing a variety of cancers." (PMID 29986057, 2018). "Mutations in genes of the breast cancer susceptibility gene (BRCA) pathway, namely, BRCA1, BRCA2, and PALB2, can provide useful information for the efficacy of platinum-based or poly ADP-ribose polymerase inhibitors chemotherapeutic regimens." (PMID 29802286, 2018). "In a clinical trial, a PARP inhibitor (PARPi) has been utilised to induce synthetic lethality of cancer cells defective in the BRCA2 gene because it blocks single-strand break repair, resulting in the formation of cytotoxic DSBs37." (PMID 29170499, 2017). "BRCA1 and BRCA2 are involved in homologous recombination (HR) DNA repair and are germ-line cancer pre-disposition genes that result in a syndrome of hereditary breast and ovarian cancer (HBOC)." (PMID 29021619, 2017). "Except for 3, the other 20 mutation hits with history of occurrence in different types of cancer including breast and ovarian have damaging effect on BRCA2 protein." (PMID 28591715, 2017). "In line with this notion, RNA sequencing analysis of Brca2 mutant cancers that were either sensitive or resistant to PARP inhibition did not provide evidence that EMI1 loss is involved in PARP inhibitor resistance." (PMID 28714471, 2017). "Consistent with previous studies, patients harboring germline BRCA1 mutant tumors had a worse TTP (p=0.023) and shorter OS (p=0.007) to PARP inhibitor monotherapy compared to patients with germline BRCA2 mutant cancers in our series of patients." (PMID 29262651, 2017). "Our data suggest that the CX drugs, and possibly other G4 stabilizers have the potential to treat cancers deficient for BRCA1, BRCA2, NHEJ pathway members and some other genes involved in DNA damage repair and DNA replication." (PMID 28211448, 2017). "Both KIF4A and its binding proteins such as PARP-1, BRCA2 and PRC1 have been implicated in multiple types of human cancers." (PMID 28160558, 2017). "Despite being a popular model organism in genetic and cancer research, knowledge on the conservation of the HR pathway and function of zebrafish Brca2 is limited." (PMID 29184099, 2017). "When classifying BRCA1 or BRCA2 mutant samples from sporadic cancers we achieved an AUC = 0.660; however, classification of only germline BRCA2 mutant tumors was inaccurate (AUC = 0.528)." (PMID 29146938, 2017). "RRSO has proven efficacy, with a reduction in “ovarian cancer” risk of 79–85%, and it is associated with lower cancer-specific and all-cause mortality in BRCA1 and BRCA2 mutation carriers." (PMID 28285341, 2017).
cancer (continued). "These alterations are generally mutually exclusive with changes in the breast cancer (BRCA) susceptibility genes BRCA1, BRCA2 or partner and localizer of BRCA2 (PALB2)." (PMID 28218679, 2017). "Essential components of HR are the tumor suppressor proteins BRCA1 and BRCA2, since their absence results in unrepaired lesions, cell-cycle arrest and cell death in cancer cells exposed to cytotoxic chemotherapy." (PMID 28482906, 2017). "The present study demonstrates that there are large differences in the absolute cancer risks between BRCA1 and BRCA2 mutation carriers with higher vs lower values of the PRS." (PMID 28376175, 2017). "In particular, two Single Nucleotide Polymorphisms (SNPs) in the OGG1 and NEIL2 genes were identified as cancer risk modifiers for BRCA1 and BRCA2 mutation carriers, respectively." (PMID 29383107, 2017). "BRCA1 and BRCA2 are two classic tumor suppressor genes that play important roles not only in tumorigenesis but also cancer progression and outcome." (PMID 28415599, 2017). "The identification of BRCA1 and BRCA2 (BRCA1/2) genes has greatly enhanced our knowledge of the DNA repair pathways involved in cancer progression and has led to the exploitation of the concept of synthetic lethality in cancer therapy." (PMID 28454085, 2017). "Several COSMIC cancer genes were found to have various mutations in multiple samples, including PTEN, PIK3CA, BRCA2, and ATM." (PMID 28852190, 2017). "A successful example of applying the synthetic lethality approach is the targeting of cancers with dysfunction of the breast-cancer susceptibility genes 1 and 2 (BRCA1 and BRCA2) by poly(adenosine diphosphate [ADP]–ribose) polymerase (PARP) inhibitors." (PMID 27880943, 2017). "Homologous recombination is defective in cancer cells with mutant BRCA1 or BRCA2 genes, leading to more genetic abnormalities." (PMID 28591715, 2017). "Cancer Australia recommends consideration of RRSO by BRCA1 and BRCA2 mutation carriers at around the age of 40 years and individualised discussion for other women at high risk in the absence of a gene mutation." (PMID 28285341, 2017). "There was also a significantly reduced OS for patients with germline BRCA1 mutant cancers versus those harboring BRCA2 mutant cancers (515 vs 937 days; HR: 0.49, 95% CI 0.29-0.83; p=0.007)." (PMID 29262651, 2017). "To date, genetic testing of BRCA1 and BRCA2 is conducted in clinical practice only, in individuals with a strong family history or after a cancer diagnosis." (PMID 29275340, 2017). "In BRCA1 and BRCA2 carriers, the cancer prevalence (and incidence) is much higher than in the cohort studied here (approximately 6-fold higher) and the use of MRI as a screening tool can be justified." (PMID 28265306, 2017). "Cancers in 31 (83.8%) of the 37 women occurred in mutation carriers—24 (64.9%) were BRCA1 carriers and seven (18.9%) were BRCA2 carriers." (PMID 28240969, 2017). "The normal function of BRCA1 and BRCA2 genes is DNA repair, transcription and recombination, all of which prevent cancer development as part of the tumor suppressor group of genes." (PMID 29021639, 2017). "Genetic tests of cancer predisposition genes, BRCA1 and BRCA2, inform significant clinical decisions for both physicians and patients." (PMID 28782058, 2017).
cancer (continued). "To explore the consequences of PARP inhibition on mitotic progression in HR-defective cancer cells, we depleted BRCA2 in HeLa cells." (PMID 28714471, 2017). "Since a high percentage of the East Asian population carries a dominant‐negative allele of the aldehyde‐catalyzing enzyme ALDH2, studies investigating cancer risk associated with BRCA1 and BRCA2 mutations in this population will be important." (PMID 28835508, 2017). "For example, in the recent paper by the Toronto group of 496 BRCA1 and BRCA2 carriers, 57 cancers were identified in 1847 screening rounds (31 per 1000) compared to 26 cancers in 5319 screening rounds (5 per 1000) in the present study." (PMID 28265306, 2017). "We then examined the ability of MPH to suppress growth and proliferation of 11 cancer cell lines harboring well-characterized different deficiencies in the HR pathways, including BRCA1−/−, BRCA2−/−, PTEN−/− and EWS-FLI1." (PMID 27926532, 2017). "Despite impressive clinical activity in patients with germline BRCA1 and BRCA2 (BRCA1/2) mutant cancers, antitumor responses to poly(ADP-Ribose) polymerase (PARP) inhibitors are variable." (PMID 29262651, 2017). "BRCA1 and 2 highest expression levels were verified in the complex carcinomas samples and in complex adenoma exclusively for BRCA2." (PMID 28945747, 2017). "For BRCA2 methylation in Sporadic-C, there was a statistically significant association only with grade: Methylation of the BRCA2.1 probe and of all four BRCA2 probes combined was more frequently seen in grade 3 carcinomas." (PMID 28569220, 2017). "From this dataset, we investigated the occurrence of TH, we compared the characteristics and features of BC and OC in TH and single BRCA1 or BRCA2 mutations, and we examined LOH in as many cancer samples as possible." (PMID 27836010, 2016). "The increased cancer susceptibility in BRCA1 and BRCA2 mutation carriers therefore can—to a large extent—be explained by chromosomal instability." (PMID 27881737, 2016). "Expression of breast cancer 1 (BRCA1), breast cancer 2 (BRCA2), cathepsin D (CTSD), BCL2, and WISP2 were significantly increased." (PMID 27379522, 2016). "BRCA1 and BRCA2 are critical for the process of DNA repair by homologous recombination repair (HRR), and deficient HRR makes cancers more susceptible to DNA-damaging agents." (PMID 27959926, 2016). "In the context of BRCA1 and BRCA2 mutation carriers, it has been shown that other factors such as single nucleotide polymorphisms (SNPs) in genes from other DNA repair pathways could cause a higher genomic instability, hence increasing the cancer risk predisposition." (PMID 27015555, 2016). "The objective of this work was to quantify the contribution of the founder mutations BRCA2 c.156_157insAlu and BRCA1 c.3331_3334del for cancer etiology in unselected hospital-based cohorts of patients diagnosed with these rarer cancers in Portugal." (PMID 27532258, 2016). "To overcome that resistance and expand use of PARP1 inhibition to cancers with functional HRR, we developed an antisense strategy to render the majority of tumor cells in a population BRCA2-deficient." (PMID 26959114, 2016). "While disease-associated mutations in RAD51 are extremely rare, depletion by siRNA or miRNA induces a “BRCAness” phenotype and sensitizes cancer cells to DNA damaging agents such as cisplatin and PARP1 inhibitors similarly, to BRCA1 and BRCA2 mutations." (PMID 26910887, 2016). "Screening for these three founder mutations is sufficient to capture nearly all inherited cancer risk in this population due to BRCA1 and BRCA2 mutations." (PMID 26867194, 2016). "Although BRCA2 mutation carriers predominantly have an increased risk of hereditary breast and ovarian cancer (HBOC), they are also at risk of other cancers such as pancreatic, gastric, laryngeal and prostate cancers." (PMID 27490902, 2016).
cancer (continued). "Cancers in which BRCA2, PALB2, or ATM have been biallelically inactivated are usually susceptible to poly(ADP-ribose) polymerase (PARP) inhibitors or platinum-based agents that facilitates double strand DNA breaks." (PMID 27732944, 2016). "Effectors of HR such as BRCA1 (Breast Cancer 1), BRCA2, MRE11A and RAD51 were significantly expressed following IR." (PMID 27495836, 2016). "Apart from founder mutations in Polish cancer patients, several other recurrent BRCA1 (185delAG, 3819del5, 3875del4, 5370C > T) and BRCA2 (886delGT, 4075delGT, 5467insT, 6174delT, 8138del5) mutations were detected." (PMID 26779294, 2016). "RB1 and BRCA2 abnormalities play a role in the development of several cancers and are considered to be tumor suppressor genes." (PMID 27741277, 2016). "We describe the design and analytic validation of the Counsyl Inherited Cancer Screen, a next-generation-sequencing-based test to detect pathogenic variation in the BRCA1 and BRCA2 genes." (PMID 27375968, 2016). "Abnormal pancreatic imaging findings including pancreatic atrophy, cysts, ductal dilation, or cancer were identified in 35% of patients with known at-risk BRCA1 and BRCA2 genetic mutations." (PMID 27069714, 2016). "Several prediction models, which consider age of onset and family history of cancer, can be used to estimate the prior probability of having a BRCA1 or BRCA2 mutation." (PMID 27553291, 2016). "With this, we would like to explain the cancer risk modifier effect that this gene exerts in carriers of BRCA1 and BRCA2 mutations." (PMID 27015555, 2016). "Clinical mutation screening of the cancer susceptibility genes BRCA1 and BRCA2 generates many unclassified variants (UVs)." (PMID 26913838, 2016). "WGS was performed on a series of patients from the cancer genetics clinic that included those found to have BRCA1 (n = 88) or BRCA2 (n = 88) mutations, as well as those that were not carriers of a BRCA1/2 mutation (n = 82)." (PMID 26023681, 2015). "In turn, the importance of Rad51 in the HR pathway is highlighted by the tumor suppressor protein BRCA2, which is involved in breast and ovarian cancers, as well as other types of cancers." (PMID 25938495, 2015). "The antibody responses to PARP1, BRCA1, and BRCA2 had strong reactivity in representative cancer sera compared to normal controls." (PMID 25865228, 2015). "As cancers in BRCA1 and BRCA2 mutation carrier subjects occur at an earlier age, identification, education and implementation of risk reduction has a high cost-to-benefit ratio in favor of benefit." (PMID 26543556, 2015). "Recent studies have highlighted importance of RAD52 in human cancer cell lines deficient in BRCA1, PALB2 or BRCA2, as its depletion led to cell death in a synthetic lethality manner." (PMID 26610585, 2015). "Noteworthy, PARP inhibitors, the first molecularly targeted anti-cancer drugs that exploit the DNA repair defect present in BRCA1- or BRCA2-mutant cancers were FDA-approved at the end of 2014." (PMID 26734064, 2015). "This rate is comparable to cancer detection rates in the high risk BRCA1 and BRCA2 mutation carrier population, for whom screening breast MRI has indeed been found to be useful and is an imaging modality recommended for wide usage." (PMID 26322264, 2015). "In the present study, miRNA expression profiles were investigated by miRNA microarray between normal and cancer tissue from BRCA1 and BRCA2 germ-line mutation carriers, in comparison with normal tissue from non-carriers." (PMID 26378051, 2015).
cancer (continued). "CIMBA is a collaborative group of researchers working on genetic modifiers of cancer risk in BRCA1 and BRCA2 mutation carriers." (PMID 25925750, 2015). "Repeating the analysis but censoring at the first cancer yielded similar results (eg, under the polygenic model BRCA1 mutation frequency was estimated to be 0.083% and BRCA2 mutation frequency was 0.27% with a polygenic SD of 1.46)." (PMID 26025000, 2015). "BRCA2 is a multisite cancer gene that not only affects women, but also increases a man’s risk of developing cancer." (PMID 26236408, 2015). "BRCA1- and BRCA2-mutant cancers exhibit differences in histopathology, gene expression profiles, and clinical course, even though they share similarities in their marked levels of genomic instability." (PMID 25699710, 2015). "From whole-genome sequences of over 1000 HCC cases entered into the Catalogue of Somatic Mutations in Cancer (COSMIC) database, rates of BRCA1 and BRCA2 mutations were 0.07 and 1.7 %, respectively." (PMID 26449224, 2015). "Numerous studies have established that cancers with a dysfunction of the HR DNA repair pathway, also referred to as “BRCAness,” share characteristics with BRCA1- or BRCA2-mutated cancer cells and are very sensitive to PARPi." (PMID 26497583, 2015). "Our studies further suggest that synthetic lethality interaction (PARP1 and BRCA1/BRCA2) only exist in certain types of cancers." (PMID 25865228, 2015). "The association of ‘early’ FA genes with FANCD2 monoubiquitination defects with increased cancer susceptibility is much weaker compared with the ‘late’ FA genes such as BRCA1, BRCA2, BRIP1, PALB2 and RAD51C." (PMID 26085575, 2015). "We focused on identifying mutations in BRCA1, BRCA2 and PALB2 and the CHEK2 c.1100delC mutation, as the risks for the development of breast and associated cancers with these genes have been determined by analysing large study populations." (PMID 26577449, 2015). "Carcinomas from Patients M and N cluster together and both have high HRD score and homozygous somatic mutations in BRCA2 and BRCA1, respectively." (PMID 25916844, 2015). "Both of these two families also had a family member with a diagnosis of another BRCA2-related cancer." (PMID 25225577, 2014). "In vitro and in vivo evidence has supported the utilization of PARP inhibitors as single agents to reduce cancer cells that possess a defect in DNA repair that additionally have BRCA1 and BRCA2 mutations." (PMID 24317580, 2014). "Thanks to a large international collaborative effort, we have been able to identify at least two SNPs that are associated with increased cancer risk in BRCA1 and BRCA2 mutation carriers respectively." (PMID 24698998, 2014). "We report that antisense-mediated reduction of IDO in cancer cells sensitized those cells to cisplatin, alone and in combination with BRCA2 siRNA downregulation." (PMID 24784564, 2014). "In two other lumB families all members were classified as non-BRCA2-like (sporadic-like), indicating that BRCA2 is less likely to be involved in the development of cancer in these families." (PMID 24479546, 2014). "Inhibiting DNA repair by targeting BRCA2 is an attractive approach to sensitize cancer cells to chemotherapy." (PMID 24784564, 2014). "The successful use of a PARP1 inhibitor for the treatment of tumor cells in which BRCA1 or BRCA2 is inactivated has provided a paradigm for the therapeutic exploitation of cancer cell addiction to a specific DNA repair pathway." (PMID 24618719, 2014). "Mutations in common cancer genes such as PTEN, BRCA1, BRCA2, are also present but at much lower prevalence in HG-SC." (PMID 24675677, 2014).